EPCAM (epithelial cell adhesion molecule)
Diseases named in the same sentence as EPCAM in open-access papers (continued):
Sharing a sentence is not in itself a finding about the gene and the disease.
triple-negative breast carcinoma (17 papers, 2010 to 2025). An invasive breast carcinoma which is negative for expression of estrogen receptor (ER), progesterone receptor (PR), and human epidermal growth factor receptor 2 (HER2). "We used a combination of CD44, CD24 and EpCam markers to isolate CSCs since previous works have shown that these markers identify a subpopulation with increased tumor-initiating capabilities in triple-negative breast cancer cell lines." (PMID 32183150, 2020). "Radioiodinated DARPin Ec1 is a promising agent for same-day imaging of EpCAM expression in triple-negative breast cancer using SPECT." (PMID 33066684, 2020). "EpCAM-independent enrichment revealed CTCs in 32.6% of the patients, especially among triple-negative breast cancer (TNBC) patients (70.0%)." (PMID 31481116, 2019). "The goal of this study was to investigate whether our previous findings could be translated to triple-negative breast cancer and to evaluate the potential of DARPin Ec1 for imaging of EpCAM in a TNBC model in vivo." (PMID 33066684, 2020). "It has been suggested that EpCAM expression in triple-negative breast cancer may be a potential target for immunotherapy, given its resistance to current targeted therapies, such as endocrine treatment and trastuzumab." (PMID 23460885, 2013). "In conclusion, we demonstrated the inhibitory effects of CDDO-Im on triple-negative breast cancer with a potential to target cancer stem cell subpopulation, as evidenced by inhibition of CD44+/CD24−/low/EpCAM+ cells and tumorsphere formation." (PMID 25229616, 2014). "The low EpCAM expression in HER2+ and triple negative breast cancers was attributed to a more mesenchymal phenotype." (PMID 21152431, 2010). "Similarly, in an in vitro and in vivo analysis of triple negative breast cancers (TNBC), reversal of EMT progression by DNA methyltransferase and histone deacetylase inhibitor treatment, decreased EpCAM cleavage and nuclear signaling with TCF4." (PMID 34209658, 2021). "Treatment with CDDO-Im significantly decreased the number of CD44+/CD24−/low/EpCAM+ cells in sphere culture, suggesting that CDDO-Im could be used as a potential agent to target cancer stem cells in triple negative breast cancer." (PMID 25229616, 2014). "Sphere culture significantly enriched the subpopulation of CD44+/CD24−/low/EpCAM+ cells, supporting the hypothesis that CD44+/CD24−/low/EpCAM+ cells are a more selective cancer stem cell subpopulation than CD44+/CD24−/low cells in triple-negative breast cancer." (PMID 25229616, 2014).
hepatoblastoma (16 papers, 2009 to 2025). Hepatoblastoma (HB) is a malignant hepatic tumor and is the most common pediatric liver cancer. "Hepatoblastomas with high expression levels of stem/progenitor cell markers (EpCAM, LIN28B, SALL4, HMGA2, AFP) are usually associated with poor prognosis." (PMID 37414763, 2023). "Presence of membranous EpCAM with nuclear β-catenin and younger diagnostic age of hepatoblastoma are predictive of serum alpha-fetoprotein levels drop after chemotherapy." (PMID 28851352, 2017). "We found that the NDMT subtype consists of HCC with stem-like features as evident by the enrichment of patients with Hepatoblastoma-like features and EpCAM." (PMID 30833661, 2019). "A recent immunohistochemistry study also showed that up to 83.6% of hepatoblastoma tumor specimens stained positive for EpCAM, a rate similar to that in our study." (PMID 28851352, 2017). "Nuclear β-catenin expression was significantly associated with membranous epithelial cell adhesion molecule (EpCAM) expression in hepatoblastoma tumor specimens." (PMID 28851352, 2017). "We identified a subgroup of hepatoblastoma patients with early-onset age (≤1.25 years) and double positive expression of membranous EpCAM and nuclear β-catenin in tumors with better chemosensitivity and better overall and native liver survival rates." (PMID 28851352, 2017). "In our study population, we showed that the presence of membranous EpCAM is highly correlated with the expression of nuclear β-catenin in hepatoblastoma." (PMID 28851352, 2017). "Patients with an earlier age of hepatoblastoma onset (≤1.25 years) who are double positive for membranous EpCAM and nuclear β-catenin in tumors have a better response to chemotherapy and better long-term outcomes." (PMID 28851352, 2017). "According to these findings it was proposed that EpCAM (CD326) could represent an important target in the context of the development of experimental immunotherapy of hepatoblastoma." (PMID 28930164, 2017). "These tumors resemble hepatoblastoma based on their early onset, their characteristic histology and the expression of specific markers such as GPC3 and EPCAM, but most importantly high MYC expression." (PMID 39529166, 2024). "The expression levels of β-catenin, EpCAM, CK19, and OV6 in our hepatoblastoma specimens are high, indicating that hepatoblasts in the early phase of liver development are a possible origin of hepatoblastoma cancer stem cells." (PMID 28851352, 2017). "We first performed a transcriptomic evaluation of the two well‐recognized hepatoblastoma cell lines, HepG2 and HUH6, using Pearson's analysis with gene signatures in the public GSE168997 dataset to elucidate IGF2′′s role in hepatoblastoma (AFP, DUSP9, GPC3, DLK1, MYC, EPCAM, KRT8, and LIN28B)." (PMID 40271711, 2025). "One of the 2 subclasses of hepatoblastoma on gene expression profiling is allied with greater genetic instability (gains of chromosomes 8q and 2p), overexpression of hepatic progenitor cell markers (AFP, Cytokeratin 19, and EpCAM), and upregulated MYC signaling." (PMID 37600579, 2023). "The other hepatoblastoma tumor showed positivity for CD10, CD9, CD81, CD105 in the absence of GD2, EpCAM, CD99, numyogenin, and CD90." (PMID 34638431, 2021).
pancreatic ductal adenocarcinoma (16 papers, 2011 to 2025). An infiltrating adenocarcinoma that arises from the epithelial cells of the pancreas. "For instance, Freed and colleagues identified two CTC subpopulations expressing epithelial cell adhesion molecule, EpCAM (CTCEpCAM), or fibroblast activation protein-alpha, FAPα (CTCFAPα), in pancreatic ductal adenocarcinoma (PDAC) patients." (PMID 38539545, 2024). "To confirm the suppressive effect of adenosine in our murine anti-EpCAM CAR T cell model, we cocultured said CAR T cells with tumour cells of the pancreatic ductal adenocarcinoma cell line Panc02-EpCAM." (PMID 36266575, 2022). "Co-expressing populations of CD24+/CD44+/EpCAM+/CD133+ with pro-tumorigenic gene expression profile were reported in pancreatic ductal adenocarcinoma." (PMID 30121075, 2018). "Our aim was to prospectively study the value of a real-time RT-PCR assay for EpCAM detection in the peripheral blood and peritoneal cavity of patients undergoing pancreatectomy for pancreatic ductal adenocarcinoma (PDAC)." (PMID 21281486, 2011). "Eventually, FF-nPES could be used for the direct analysis of EV epithelial cell adhesion molecule (EpCAM) expression from serum in order to differentiate the early stage of pancreatic ductal adenocarcinoma patients from healthy controls." (PMID 32854390, 2020). "While screening pancreatic ductal adenocarcinoma (PDAC) human samples, it was shown that the SUV4-20H2 reported reduced levels, contributing to the establishment of the epithelial state, as demonstrated through E-cadherin and epithelial cell adhesion molecule (EPCAM)." (PMID 38473745, 2024).
prostate tumors (16 papers, 2012 to 2025). "Our data also indicated that silencing EpCAM increased prostate tumour xenograft sensitivity to chemotherapy and radiation, and significantly prolonged the survival of tumour-bearing mice." (PMID 30419852, 2018). "EpCAM expression in prostate tumor tissue is also a significant predictor of shorter biochemical recurrence free-survival." (PMID 24885350, 2014). "The average concentration of EpCAM was 9.39 ± 4.22 ng/mg total protein for normal tissues and 44.61 ± 23.40 ng/mg for prostate tumors." (PMID 24289299, 2013). "Subsequently, using the in-house developed method, we estimated the epithelium percentage of the 8 normal prostate tissues and 36 prostate tumors whose EpCAM and CTSL levels were measured." (PMID 24289299, 2013). "Compared to normal tissues, immunoassay data showed that both EpCAM and CTSL expression were significantly increased in prostate tumors with a 4.75 fold increase for EpCAM and a 1.88 fold increase for CTSL." (PMID 24289299, 2013). "In 40% to 60% of prostate tumors, epithelial cell adhesion molecule (EpCAM) is overexpressed." (PMID 37746426, 2023). "Prostate tumor-derived cells express the surface marker EpCAM." (PMID 25595903, 2015). "Western blot analysis data demonstrated exceptional enrichment of exosomal markers (TSG 101, CD9) and epithelial cell adhesion molecule (EpCAM), as well as moderately enriched prostate tumor-marker PSMA in exosomes when compared to relatively stable α-tubulin levels in cells and exosomes." (PMID 24424840, 2014). "EpCAM is a putative stem cell marker in breast, liver, colon, pancreas, and prostate tumors." (PMID 23213278, 2012). "With EpCAM and CTSL expressions in prostate tumor tissues, we demonstrated that normalization by epithelial percentage is useful in analyzing ELISA results for epithelial proteins." (PMID 24289299, 2013). "With both epithelium estimations, EpCAM expression was significantly increased in prostate tumors by about 2 fold, compared to the 4.75 fold increase without normalization." (PMID 24289299, 2013).
retinoblastoma (16 papers, 2010 to 2025). A malignant tumor that originates in the nuclear layer of the retina. "Au nanorods, when combined with anti-epithelial cell adhesion molecule (EpCAM), accurately target EpCAM+Y79 retinoblastoma cancer cells." (PMID 39995756, 2025). "Using fresh retinoblastoma tissue, the co-expression of EpCAM and three other putative tumor stem cell markers CD44, CD24 and ABCG2 was examined." (PMID 36132125, 2022). "A high percentage of cells in retinoblastoma express EpCAM, and especially tumors with optic nerve/choroidal invasion demonstrate increased EpCAM expression." (PMID 36132125, 2022). "Recently, we demonstrated an EpCAM antibody-based targeted approach for enhanced drug delivery to EpCAM-expressing retinoblastoma (RB) Y79 cells using EpCAM antibody conjugated polymeric nanoparticles loaded with chemotherapy drugs." (PMID 23687439, 2013). "A high proportion of cells in retinoblastoma express EpCAM, and tumors with optic nerve/choroidal invasion in particular show increased EpCAM expression." (PMID 22328825, 2012). "This is the first study to show the relationship between the EpCAM and miR 17–92 cluster in retinoblastoma." (PMID 22969266, 2012). "In the present study, we attempted to determine the relationship between EpCAM and the miR 17–92 cluster in retinoblastoma." (PMID 22969266, 2012). "Therefore, the invasive retinoblastoma is an attractive tumor for therapeutic targeting using a bispecific antibody (EpCAM × CD3)." (PMID 36132125, 2022). "In this milieu, we hypothesize that EpCAM may also be involved in regulating the miR 17–92 cluster in retinoblastoma." (PMID 22969266, 2012). "EpCAM influences miR 17–92 cluster expression in retinoblastoma." (PMID 22969266, 2012). "Epithelial cell adhesion molecule (EpCAM) gene is involved in many epithelial cancers including, retinoblastoma (RB) tumorigenesis." (PMID 25502397, 2014). "EpCAM has not been associated with any of the cancer stem cell markers in retinoblastoma." (PMID 22328825, 2012). "In this study we characterized the EpCAM+ retinoblastoma (RB) cells for their cancer stem-like properties in vitro." (PMID 22328825, 2012). "In this study, internalization of the EpCAM antibody-conjugated AuNP-PEI and delivery of the EpCAM siRNA resulted in a significant downregulation of EpCAM gene expression and viability in retinoblastoma Y79 cells." (PMID 38612911, 2024). "In the present review, we described the latest innovations in retinoblastoma immunotherapy targeting GD2, PD-1, B7H3, EpCAM and SYK." (PMID 36132125, 2022). "The EpCAM is over expressed in Y79 and WERI-Rb1 retinoblastoma cell lines and Nthy-ori 3-1 normal cell line." (PMID 24391761, 2013). "In the present study, we prepared novel epithelial cell adhesion molecule (EpCAM) monoclonal antibody conjugated polyethyleneimine (PEI) capped gold nanoparticles (AuNPs) loaded with EpCAM-specific siRNA molecules to knock-down the EpCAM gene in retinoblastoma (RB) cells." (PMID 23687439, 2013). "In the present study, besides demonstrating EpCAM as a cancer stem cell marker, we investigated the antitumor efficacy of EpCAM×CD3 bispecific antibody in retinoblastoma primary tumors." (PMID 22328825, 2012). "Hence, we used the EpCAM-targeted therapeutic approach for retinoblastoma using an aptamer against EpCAM, and this is the first study using the EpCAM aptamer for targeted drug delivery in RB cells." (PMID 23213278, 2012). "Previously we showed that epithelial cell adhesion molecule (Ep-CAM), a cell surface molecule, was highly expressed in primary retinoblastoma tumors." (PMID 20461151, 2010). "EpCAM levels are considerably higher in retinoblastoma (RB), a childhood eye cancer with limited expression in normal cells." (PMID 24391761, 2013). "The transfection of EGP2-TK-2T construct restricted the TK expression only in retinoblastoma cell lines (lane 3, 4) and not in normal cell lines such as MIO-M1 and Nthy-ori 3-1 even in the presence of EpCAM protein." (PMID 24391761, 2013).
retinoblastoma (continued). "Epithelial cell adhesion molecule (EpCAM), a cancer stem cell (CSC) marker is over expressed in epithelial cancers and in retinoblastoma (RB)." (PMID 26176230, 2015).
cervical carcinoma (15 papers, 2012 to 2025). A carcinoma arising from either the exocervical squamous epithelium or the endocervical glandular epithelium. "Simultaneously, a loss of EpCAM expression was observed in Slug-overexpressing cervical cancer cell lines." (PMID 33691694, 2021). "In our previous study, SNAI2 exhibited the capacity to inhibit cell proliferation, and promote cell motility and distant metastasis by trans-suppressing EPCAM expression in cervical cancer." (PMID 36674577, 2023). "In our previous study, SNAI2 exhibited the capacity to act as a transcriptional repressor of EPCAM in cervical cancer." (PMID 36674577, 2023). "Although the advantageous effect of EPCAM on regulating cell stemness has been reported in various cancers, it has been rarely studied in cervical cancer." (PMID 36674577, 2023). "Further studies revealed the trans-suppression effect of Slug through its binding to the proximal promoter region of EpCAM to inhibit the expression of EpCAM in cervical cancer cells." (PMID 33691694, 2021). "Further studies revealed the trans-suppression effect of Slug on EpCAM through its binding to the E-boxes in the proximal promoter region of EpCAM in cervical cancer cells." (PMID 33691694, 2021). "Further luciferase reporter and chromatin immunoprecipitation assays corroborated the trans-suppression effect of Slug on EpCAM in cervical cancer cells via its binding to an alternative sequence site upstream of the EpCAM promoter." (PMID 33691694, 2021). "In cervical cancer, the aberrant expression of EpCAM has been reported, and the presence of EpCAM in cervical adenosquamous carcinoma (ASC) is related to radiosensitivity." (PMID 33691694, 2021). "SLUG-positivity was detected in a considerable proportion of CD45 (-) EpCAM (+) cells in cervical cancer precursor lesions, but a notably lower number of CD45 (-) CK (+) cells stained positively for SLUG in all stages examined." (PMID 32899940, 2020). "Correspondingly, the ratio CK (+)/EpCAM (+) cells (in %) displayed a tendency toward increase in invasive cervical cancer samples as compared the control." (PMID 32899940, 2020). "Only the anti-EpCAM MAb to the membrane-proximal part is able to detect EpCAM on paraffin-embedded cervical cancer tissues." (PMID 29202724, 2017). "The IHC score of EpCAM expression was strongly correlated with cervical cancer and grades of precancerous lesions (r=0.875, p<0.001)." (PMID 29202724, 2017). "An example of these antibodies is the adecatumum (MT201), a humanized monoclonal antibody targeting epithelial cell adhesion molecules, showing activity in cervical cancer cell lines over-expressing epithelial cell adhesion molecule (EpCAM)." (PMID 24667138, 2014). "Our previous study demonstrated that SNAI2 could inhibit EPCAM expression by recognizing and directly binding the E-box motifs (CANNTG) in the proximal promoter region of EPCAM in cervical cancer cells, further inhibiting cell proliferation, and inducing EMT." (PMID 36674577, 2023). "All of these results demonstrated that SNAI2 could attenuate the stem-like phenotype in cervical cancer cells through the EPCAM/β-catenin axis." (PMID 36674577, 2023). "EPCAM is considered a multifunctional transmembrane protein involved in the regulation of cell stemness and is required for stem cell survival or proliferation, and the inhibitory role of SNAI2 on trans-suppressing EPCAM expression in cervical cancer was reported in our previous study." (PMID 36674577, 2023). "Finally, these data identified an upstream sequence site of EpCAM (− 987 ~ CAGGTG~ − 981) that was described as a selected binding site for Slug to transcriptionally inhibit EpCAM in cervical cancer cells." (PMID 33691694, 2021). "All of these results suggest that the presence of EpCAM in cervical cancer cells could promote cell proliferation but attenuate cell motility." (PMID 33691694, 2021).